FGF22 (fibroblast growth factor 22)
Description:
Plays a role in the fasting response, glucose homeostasis, lipolysis and lipogenesis. Can stimulate cell proliferation (in vitro). May be involved in hair development.
Tractability: Antibody: UniProt places it where antibodies can reach, with high confidence; its Gene Ontology location is reachable by antibodies, with high confidence; UniProt predicts a signal peptide or a membrane-spanning region.
Target class: Secreted protein
Gene: Protein-coding gene on chromosome 19 (639,879 to 644,373, forward strand). Ensembl gene ENSG00000070388.
Subcellular location: Secreted
Pathways (Reactome):
Signal Transduction: Downstream signaling of activated FGFR1; FGFR1b ligand binding and activation; FGFR2b ligand binding and activation; FGFRL1 modulation of FGFR1 signaling; FRS-mediated FGFR1 signaling; FRS-mediated FGFR2 signaling; Negative regulation of FGFR1 signaling; Negative regulation of FGFR2 signaling; PI-3K cascade:FGFR1; PI-3K cascade:FGFR2; PI3K Cascade; PI5P, PP2A and IER3 Regulate PI3K/AKT Signaling; PIP3 activates AKT signaling; Phospholipase C-mediated cascade: FGFR1; Phospholipase C-mediated cascade; FGFR2; RAF/MAP kinase cascade; SHC-mediated cascade:FGFR1; SHC-mediated cascade:FGFR2
Disease: Activated point mutants of FGFR2; Constitutive Signaling by Aberrant PI3K in Cancer; Signaling by FGFR2 in disease
Gene Ontology:
Molecular function: fibroblast growth factor receptor binding; growth factor activity
Biological process: cell differentiation; fibroblast growth factor receptor signaling pathway; neurogenesis; positive regulation of cell population proliferation; positive regulation of MAPK cascade; regulation of cell migration; regulation of synapse maturation; trans-synaptic signaling
Cellular component: cytoplasm; extracellular region; cell surface; extrinsic component of postsynaptic density membrane; GABA-ergic synapse; glutamatergic synapse; Golgi apparatus; nucleolus; postsynapse
Genetic constraint (gnomAD): Loss-of-function variants: 11 observed, 6.21 expected, observed/expected ratio (o/e) 1.77, 90% interval 1.02 to 1.96. That is too few expected variants to judge how well the gene tolerates losing a copy. Missense variants: 317 observed, 222.29 expected, observed/expected ratio (o/e) 1.43, 90% interval 1.3 to 1.57. Synonymous variants: 136 observed, 94.19 expected, observed/expected ratio (o/e) 1.44, 90% interval 1.25 to 1.66.
Homologues: Orthologues: chimpanzee FGF22 (99% identical), mouse Fgf22 (81% identical), dog FGF22 (80% identical), guinea pig FGF22 (78% identical), pig FGF22 (76% identical), rat Fgf22 (74% identical), macaque FGF22 (68% identical), zebrafish fgf22 (51% identical), tropical clawed frog fgf22 (47% identical). Paralogues in human: FGF10 (47% identical), FGF3 (41% identical), FGF7 (40% identical), FGF20 (38% identical), FGF9 (36% identical), FGF16 (35% identical), FGF4 (34% identical), FGF5 (34% identical), FGF11 (32% identical), FGF6 (32% identical), FGF1 (29% identical), FGF14 (29% identical), and 9 more.